PPT1 (palmitoyl-protein thioesterase 1)
Diseases named in the same sentence as PPT1 in open-access papers (continued):
Sharing a sentence is not in itself a finding about the gene and the disease.
tumor (continued). "We further constructed gene modules in AT2 (LUAD) and basal (LUSC) cells, which revealed that many tumor-related genes in cells from stage-I patients, including PIGR, AZGP1, BTG2, EGR1, and LMO3 in AT2 cells from LUAD, and AQP3, SPHK1, PPT1, and PDIA6 were found in basal cells from LUSC." (PMID 35027529, 2022). "In order to reduce the side effects of PPT1 inhibitor DC661, smart organic nanocarriers with self-adaptive responsiveness for improving tumor drug delivery and curative effect might have broad application prospects." (PMID 35277179, 2022). "Combined with the anti-PD-1 therapy, CQ/HCQ targeting palmitoyl protein thioesterase 1 (PPT1), a novel regulator of cancer cell autophagy, enhances the anti-tumor immune response by switching the macrophage M2 to M1 phenotype, lowering MDSCs, and increasing T cell-mediated cytotoxicity." (PMID 36300110, 2022). "Since Ulk1, Vps34, and Atg7 represent the key nodes of the autophagy pathway, these results indicate that the effects of Ppt1 inhibitors are independent of the autophagy pathway in tumor cells at least in the B16 model." (PMID 32780726, 2020). "Data presented here are consistent with increased anti-tumor immunity and restricted tumor growth observed in knockout mice lacking the expression of palmitoyl-protein thioesterase 1, which normally acts to increase lysosomal activity and to promote antigen degradation in DCs64." (PMID 36333297, 2022).
cancer (32 papers, 2020 to 2025). A tumor composed of atypical neoplastic, often pleomorphic cells that invade other tissues. "Recent studies have revealed that palmitoyl-protein thioesterase 1 (PPT1) is closely associated with the initiation, progression, and drug resistance of various malignant tumors." (PMID 40416361, 2025). "Higher expression levels of PPT1 in tumors are associated with shorter overall survival for a variety of cancers, including head and neck, esophageal, and renal cell cancers." (PMID 35277179, 2022). "GNS561 is a novel PPT1 inhibitor that has garnered significant attention for its potent antitumor activity across various cancers." (PMID 40416361, 2025). "One promising direction is the targeting of GNS561, a selective inhibitor of PPT1, currently under investigation for cancer therapy." (PMID 40703511, 2025). "Palmitoyl-protein thioesterase 1 (PPT1), a molecular target of HCQ, Lys05, and DC661, is overexpressed in various cancers and is associated with poor prognosis." (PMID 39456967, 2024). "Targeted inhibition of PPT1 disrupts both the mTOR pathway and lysosomal function, signaling a new direction in cancer therapy." (PMID 38067206, 2023). "The novel compound DQ661, a dimeric quinacrine derivative, highlights the crucial role of PPT1 in lysosomal function, with implications for cancer and therapeutic resistance." (PMID 38067206, 2023). "The function and role of selected genes in the lysosome have been investigated, previous studies have found that PPT1 in tumors correlates with poor survival in patients in a variety of cancers." (PMID 37103469, 2023). "In conclusion, the interconnection between palmitoylation and autophagy, reinforced by novel insights into PPT1, offers a hopeful prospect for innovative cancer treatments." (PMID 38067206, 2023). "For example, patients with overexpression of PPT1 showed poorer survival in multiple cancers, suggesting the potential of PPT1 inhibition strategies in cancer therapy." (PMID 36286021, 2022). "These proteins were studied for their implication in cancer: PPT1 is involved in lysosomal degradation and its high expression is correlated with a worse prognosis in cancer settings." (PMID 36291699, 2022). "Palmitoyl-protein thioesterase 1 (PPT1), also identified in stage 0–I, is increased in cancer and associated with poor survival." (PMID 34439311, 2021). "Conditioned media from macrophages treated with Ppt1 inhibitors were able to enhance T cell–mediated cancer cell killing." (PMID 32780726, 2020). "In addition, higher expression levels of PPT1 in tumors are correlated with shorter overall survival for a variety of cancers." (PMID 37434985, 2023). "Accordingly, if autophagy cargo receptors are secreted during DC661-mediated lysosomal inhibition, one can speculate that these proteins may serve as noninvasive biomarkers to monitor the efficacy of PPT1 inhibition during cancer treatment." (PMID 37066873, 2023). "Palmitoyl-protein thioesterase 1 (PPT1) plays a critical role in progression of various cancers." (PMID 35277179, 2022). "A recent preclinical study described palmitoyl-protein thioesterase 1 (PPT1), a lysosomal enzyme whose expression is correlated with a poor prognosis in cancer patients, as the point of attack for the autophagy modulating and antineoplastic activity of CQ and its derivative DC661." (PMID 34771737, 2021). "To date, the role of PPT1 in cancer immunotherapy has remained unexplored." (PMID 32780726, 2020). "Therefore, the development of potent PPT1 inhibitors is of strong interest in cancer." (PMID 37443736, 2023). "DC661 surpasses hydroxychloroquine in inhibiting autophagy by targeting PPT1, while GNS561 shows potential synergy with immune checkpoint inhibitors, marking a shift in cancer treatment strategies." (PMID 38067206, 2023).
cancer (continued). "Given its opposite action in cDC1s and pDCs, PPT1 may be a potential pharmaceutical inhibitory target for SLE treatment, due to possible added benefit of enhancing the CTL response against cancer and pathogens." (PMID 38169466, 2024). "Similarly, the modulation of cancer cell lysosomal activity by blocking PPT1 represents another promising new target, especially in the context of the enhancement of ICI activity with PPT1 blockade." (PMID 39267840, 2024). "Genetic suppression of core autophagy genes, but not Ppt1, in cancer cells reduced priming and cytotoxic capacity of primed T cells." (PMID 32780726, 2020).
neurodegenerative disease (21 papers, 2007 to 2025). A disorder of the central nervous system characterized by gradual and progressive loss of neural tissue and neurologic function. "Loss-of-function mutations in the depalmitoylating enzyme palmitoyl protein thioesterase 1 (PPT1) lead to deficient depalmitoylation and synaptic function and result in the neurodegenerative disease NCL type 1 (CLN1)." (PMID 35358180, 2022). "Further, despite the finding that loss-of-function mutations affecting palmitoyl-protein thioesterase 1 (PPT1) function cause a severe pediatric neurodegenerative disease, the role of PPT1 as a depalmitoylase has attracted relatively little attention." (PMID 31555119, 2019). "Some neurodegenerative diseases in humans are caused by mutations in Ppt1." (PMID 30759161, 2019). "This study contributes valuable insights into the development of natural product-based therapeutics for neurodegenerative diseases by identifying amentoflavone as a promising candidate for PPT1 inhibition." (PMID 39807377, 2024). "Targeting PPT1 might enable modulation of the protein palmitoylation/depalmitoylation balance, which has been implicated in AD and other neurodegenerative conditions, thus leading to the development of therapeutic strategies for treating neurodegenerative diseases." (PMID 39807377, 2024). "PPT1-related NCL is a devastating early onset neurodegenerative disease, and as such, is considered a likely candidate for gene therapy and for enzyme-related therapeutic approaches." (PMID 26731412, 2016). "While PPT1 is associated with neuronal disorders, little is known about the function of PPT2, despite its crucial role in the search for therapeutic solutions against neurodegenerative diseases in humans." (PMID 33670203, 2021). "Collectively, these data highlight the role of PPT1 in mediating synapse functions, implicate molecular pathways in the etiology of NCL and other neurodegenerative diseases, and advance our basic understanding of the purpose of depalmitoylation." (PMID 35358180, 2022). "Hindering GFAP palmitoylation rescue both astrogliosis and neurodegenerative pathology in PPT1-KI mice and hereby offer palm-C291 in GFAP as a possible pharmaceutical target for curing INCL and other possible neurodegenerative diseases." (PMID 33753498, 2021).
infection (9 papers, 2012 to 2025). The state of being infected such as from the introduction of a foreign agent such as serum, vaccine, antigenic substance or organism. "Overexpressing PPT1 on hematopoietic stem cells by infection of lentivirus (LV), which are then delivered intravenously (IV), has been shown to extend the lifespan of CLN1‐deficient mice from approximately 250 days to over 350 days." (PMID 39925015, 2025). "Correspondingly, pDC cell number was higher in PPT1-deficient mice than PPT1-sufficient mice after infection with HSV." (PMID 38169466, 2024). "We observed a reduced IFNα serum concentration in PPT1-deficient mice after infection with HSV." (PMID 38169466, 2024). "The data obtained from pathogenicity assays of fluorescently labeled F. fujikuroi ppt1 mutants in hydroponic rice cultures indicate that lysine production and iron uptake are essential for the establishment of infection of the rice roots." (PMID 22662164, 2012). "However, when lysine was supplemented, wild-type-like infection structures of the ppt1 mutant could be observed, indicating that the reductive iron uptake systems of F. fujikuroi are sufficient for iron acquisition during infection." (PMID 22662164, 2012).
neurological disease (6 papers, 2019 to 2025). "In regard to a possible late-onset neurologic disease in older dogs homozygous for PPT1 variants, we were able to contact owners as well as referring veterinarians and follow up five older dogs homozygous for the PPT1 complex variant and affected with PRAPPT1." (PMID 30541930, 2019). "Here, we will briefly introduce the rapidly growing field surrounding protein palmitoylation and depalmitoylation, then will focus on the role of PPT1 in development, health, and neurological disease." (PMID 31555119, 2019). "In other neurological diseases, preclinical and clinical studies suggest that mimicking the activity of depalmitoylating enzymes—such as palmitoyl-protein thioesterase 1 (PPT1)—may offer therapeutic benefit." (PMID 40703511, 2025).
genetic disorder (2 papers, 2019 to 2021). "Palmitoyl-protein thioesterase 1 (PPT1) facilitates the morphological development of neurons, synaptic function in mature cells, and is the first depalmitoylating enzyme to be linked to a genetic disorder." (PMID 31555119, 2019).
autosomal recessive disease (1 paper, 2021). Autosomal recessive form of disease. "INCL is an autosomal recessive disease caused by loss of function mutations in the CLN1 gene, residing on chromosome 1p32, which encodes for the lysosomal enzyme Palmitoyl Protein Thioesterase 1 (PPT1)." (PMID 33561134, 2021).
cardiac disease (1 paper, 2025). "Furthermore, in addition to its role in autophagy, PPT1 functions as a depalmitoylation enzyme, regulating palmitoylation modifications in cardiac disease." (PMID 40539882, 2025).
movement disorder (1 paper, 2015). Neurological conditions resulting in abnormal voluntary or involuntary movement, which may impact the speed, fluency, quality and ease of movement. "Moreover, the terms: inhibition of organismal death, movement disorders and concentration of lipid were predicted to be altered in the PPT1 network." (PMID 26217791, 2015).
neurodevelopmental disorder (1 paper, 2014). A behavioral and cognitive disorder with onset during the developmental period that involves impaired or aberrant development of intellectual, motor, or social functions. "To examine this gene network specifically in neurodevelopmental disorders, we searched human genetic data for variants within CISD2, PPT1, CLN3 and the other 19 human genes identified by network analysis in humans." (PMID 24705017, 2014).
PPT1 also shares sentences with these, for which no sentence is quoted: colon carcinoma (4 papers); retinopathy (4); Cerebellar atrophy (3); CLN5 disease (3); diabetes mellitus (3); Gaucher disease (3); Parkinson disease (3); Alzheimer disease (2); CLN2 disease (2); cognitive decline (2); COVID-19 (2); Jansky-Bielschowsky disease (2); Niemann-Pick disease type C (2); osteosarcoma (2); Parkinson (2); retinal dystrophies (2); Anxiety (1); Ataxia (1); atherosclerosis (1); Atrophy (1); autoimmune disease (1); Cachexia (1); Cerebral atrophy (1); cholangiocarcinoma (1); ciliopathy (1); clear cell renal cell carcinoma (1); CLN3 disease (1); CLN6 disease (1); colitis (1); colon adenocarcinoma (1).
A further 44 diseases each share a sentence with PPT1 in 1 paper.